PKP3 (plakophilin 3)
Diseases named in the same sentence as PKP3 in open-access papers (continued):
Sharing a sentence is not in itself a finding about the gene and the disease.
cancer (20 papers, 2014 to 2025). A tumor composed of atypical neoplastic, often pleomorphic cells that invade other tissues. "Paradoxically, evidence has emerged that shows an upregulation of some desmosomal components, such as Dsg2, Dsg3 and Pkp3 in cancer, in association with cancer progression and/or reduced survival." (PMID 25629808, 2015). "Therefore, it is necessary to further understand the mechanisms by which PKP1 and PKP3 are downregulated and how their loss promotes cancer progression." (PMID 34203070, 2021). "PKP3 plays a crucial role in the development and progression of cancer by promoting malignant biological activity and is considered an essential biomarker for early cancer diagnosis and prognosis evaluation." (PMID 38342890, 2024). "Initially, an examination was conducted on the expression of PKP3 mRNA in various types of cancers by utilizing a pan-cancer dataset obtained from TCGA." (PMID 37760912, 2023). "Previous studies confirmed that PKP1 and PKP3 levels are elevated in several cancer tissues compared to normal tissues and regulate the proliferation and invasive capacity of cancer cells." (PMID 37924160, 2023). "The expression of different catenin molecules in different cancer tissues was inconsistent, and several molecules, including PKP3, PKP2, PKP1, and JUP, were overexpressed in several cancer tissues." (PMID 37924160, 2023). "Recently, several studies have documented increased levels of PKP3 in human cancers, indicating the possible contribution of PKP3 in the promotion of cancer." (PMID 37760912, 2023). "The expression level of GSTP1, FAM83H, TP53AIP1, and PKP3 were all reported to be involved in the development of cancer or affecting patients’ survival rate." (PMID 35776767, 2022). "CircIGF2BP3 disrupted cancer immune response through upregulating PKP3 expression via miR-328-3p and miR-3173-5p." (PMID 36545327, 2022). "circIGF2BP3 competitively upregulates PKP3 expression by sponging miR-328-3p and miR-3173-5p to compromise the cancer immune response." (PMID 34416901, 2021). "Additionally, there were DMRs overlapping with the gene bodies of METAP1D, RGPD8, and PKP3, which have been shown to be up-regulated in LUAD and promote cancer growth, and whose methylation status has been linked to in utero nicotine exposure." (PMID 37742993, 2023). "Cancer cells also overexpress PKP3 which is a WNT antagonist." (PMID 35453754, 2022). "Above studies suggested that the role of PKP3 in malignant tumors may depend on tissue types, cell types, differentiation degree and potential signal pathway." (PMID 33088217, 2020). "VIM, LGALS1, SERPINE1, PKP3 and the CDH1‐CDH2 switch were consistently altered in all the EMT models and have all been related to EMT in different cancer types." (PMID 34942055, 2022).
genetic disease (1 paper, 2014). "Here, we report the association and positive functional interaction of Pkp3 with a transcription factor, Ets variant gene 1 (ETV1), which has critical roles in neural development and prominent roles in human genetic disease." (PMID 24475179, 2014).
immune diseases (1 paper, 2023). "The enrichment findings showed that pathways connected with immune cells, immune diseases, and cytokines were enriched in the PKP3-low expression group, including natural killer cell-promoted cytotoxicity, the T-cell receptor signaling pathway, and the chemokine signaling pathway." (PMID 37760912, 2023).
PKP3 also shares sentences with these, for which no sentence is quoted: lymph node metastasis (2 papers); adenocarcinoma (1); breast invasive carcinoma (1); bullous pemphigoid (1); cicatricial pemphigoid (1); cystic fibrosis (1); diabetes (1); gastrointestinal tumor (1); Insulin resistance (1); malignant pleural mesothelioma (1); Obesity (1); ovarian serous cystadenocarcinoma (1); pneumonia (1); polycystic ovary syndrome (1); stomach cancer (1); ulcerative colitis (1).